NOX4 (NADPH oxidase 4)
Diseases named in the same sentence as NOX4 in open-access papers (continued):
Sharing a sentence is not in itself a finding about the gene and the disease.
liver fibrosis (62 papers, 2012 to 2025). "Hepatocytes also express NOX isoforms, including NOX1, NOX2 and NOX4, which have been implicated in critical steps in initiating liver fibrosis, including hepatic stellate cell activation and hepatocyte apoptosis." (PMID 35740948, 2022). "Our study showed that the intestinal bacteria changed during liver fibrosis, and this change was closely associated with UA-mediated inhibition of the NOX4/NLRP3 inflammasome signaling pathway." (PMID 34530693, 2021). "The NOX4/NLRP3 inflammasome pathway plays a crucial role in liver fibrosis and is closely associated with the beneficial effect of UA." (PMID 34530693, 2021). "We identified 10 novel lncRNAs associated with liver fibrosis, with Met and Nox4 as their target genes." (PMID 34597331, 2021). "The underlying epigenetic mechanism whereby TGF-β activates NOX4 transcription to promote EndMT and liver fibrosis, however, remains incompletely understood." (PMID 31750301, 2019). "The aim of this work was to study the functional role of NOX4 in different cell populations implicated in liver fibrosis: hepatic stellate cells (HSC), myofibroblats (MFBs) and hepatocytes." (PMID 23049784, 2012). "Moreover, four potential cis-acting targets associated with hepatic fibrosis were identified as labeled by Gsta3, Met, Nox4, and Pdgfd, and their reliability was confirmed by validation experiments." (PMID 34597331, 2021). "The mechanism by which the NOX4/NLRP3 inflammasome pathway is involved in liver fibrosis may be associated with disordered intestinal bacteria." (PMID 34530693, 2021). "This study aimed to explore whether the effect of ursolic acid (UA) on liver fibrosis was associated with the NOX4/NLRP3 inflammasome pathways and intestinal bacteria." (PMID 34530693, 2021). "In addition, analysis of the composition of the flora at the level of the phylum and genus also suggested the decline in Firmicutes and Lactobacillus caused by liver fibrosis has partially restore in the liver fibrosis mice with NOX4 or RhoA intervention." (PMID 32083022, 2020). "Accumulating evidence indicates that NOX-mediated ROS production has a critical role in hepatic fibrosis, and in particular, NOX4 is involved in the severity of HCV-associated liver disease, as well as in the regulation of viral replication of different viruses." (PMID 30906503, 2019). "In addition, NOX4 has also been found to be increased in patients with hepatitis C virus (HCV)-associated liver fibrosis and in patients with non-alcoholic steatohepatitis." (PMID 27345301, 2016). "Here we report for the first time a direct comparison of the long-term effects of NOX1 and NOX4 deficiency in the development and progression of liver fibrosis, by comparing liver fibrosis in CCl4-induced NOX1KO and NOX4KO mice and their respective wild-type (WT) littermates." (PMID 26222337, 2015). "We report for the first time a direct comparison of the long-term effects of NOX1 and NOX4 deficiency in the development and progression of liver fibrosis, by comparing liver fibrosis in CCl4-induced NOX1KO and NOX4KO mice and their respective wild-type (WT) littermates." (PMID 26222337, 2015). "Deficiency of NOX1 and NOX4 attenuates liver fibrosis in mice after CCl4 treatment." (PMID 26222337, 2015). "NOX1 or NOX4 deficiency reduced lipid peroxidation and ROS production in mice with liver fibrosis." (PMID 26222337, 2015). "Results presented here indicate that induction of NOX4 occurs in three different animal models of liver fibrosis and in chronic HCV infection in humans, associated with activation of the TGF-β pathway, appearance of fibrotic areas and hepatocyte proliferation and apoptosis." (PMID 23049784, 2012). "Thus, we hypothesize that deficiency of either NOX1 or NOX4 attenuates HSCs activation and liver fibrosis." (PMID 26222337, 2015).
liver fibrosis (continued). "Considering that NOX4 and ROS generation in activated HSCs play an important role in liver fibrosis, GSH improves ADSC engraftment efficiency in liver fibrotic mice partly through inhibiting the NOX4/ROS pathway." (PMID 40060764, 2025). "It is widely acknowledged that the TGFβ1/SMAD3 pathway plays a key role in excessive ROS generation in liver fibrosis, and TGFβ1 can regulate NOX4/ROS pathway through SMAD3 signaling." (PMID 40060764, 2025). "Overall, our study demonstrates that GSH can improve the engraftment efficiency of ADSCs in liver fibrosis by inhibiting the TGFβ1/SMAD3/NOX4 signaling pathway." (PMID 40060764, 2025). "The terpenoid Rg1 ameliorated aging-induced liver fibrosis in SAMP8 mice through the inhibition of NADPH oxidase 4/NACHT, LRR, and PYD domain-containing protein 3 (NOX4/NLRP3) inflammasome activation." (PMID 38002283, 2023). "NOX4 is found to be involved in activation of myofibroblasts followed by progression of hepatic fibrosis." (PMID 37044213, 2023). "For instance, Ang II induces liver fibrosis in chronic liver diseases by NLRP3 inflammasome activation through a NADPH-oxidase 4- (NOX4-) and H2O2-dependent mechanism." (PMID 37476705, 2023). "More and more research showed that the increase of NOX4 activity and ROS production resulted in oxidative stress to promote HSCs activation and subsequently lead to liver fibrosis." (PMID 35035671, 2022). "NOX1, NOX2, and NOX4 are involved in initiating liver fibrosis, and NOX4 plays a role in mediating TGFβ-1 signaling which is crucial in IPF development." (PMID 35740948, 2022). "Studies have shown that ursolic acid (UA) can regulate EMT or MFB via Rho, improve the integrity of the intestinal barrier, reduce intestinal flora disorders, and modulate the NOX4/NLRP3 inflammatory vesicle signaling pathway to attenuate liver fibrosis." (PMID 35529927, 2022). "After inducing liver fibrosis, melatonin restored the redox balance by decreasing the levels of ROS, NADPH oxidase 4 (NOX4), iNOS, and MDA, and by rising the activity of several antioxidant enzymes, and the expression of SOD, CAT, and GSH." (PMID 35404472, 2022). "Numerous studies have shown that NOX4-mediated oxidative stress is closely related the liver fibrosis." (PMID 35035671, 2022). "In bile duct ligation-induced liver fibrosis, pharmacological NOX4 inhibitor alleviated liver fibrosis, hepatocyte apoptosis and ROS production." (PMID 35035671, 2022). "NOX4 is expressed in hepatocytes, stellate cells and endothelial cells, and is also related to hepatic fibrosis, even in those of EtOH etiology." (PMID 35204242, 2022). "HSCs produce NOX1, NOX2, and NOX4, which play substantial roles in the process and development of liver fibrosis." (PMID 36544529, 2022). "Accumulating evidence showed that NOX4 was the vital mediator in the activation of HSCs and the development of hepatic fibrosis." (PMID 35035671, 2022). "As discovered in current studies, NOX4 is related to liver fibrosis, and the suppression of NOX4 can inhibit liver fibrosis, while acute liver injury (ALI) is the early pathological process of liver fibrosis." (PMID 35832027, 2022). "And the expression level of NOX4 was correlated with the degree of liver fibrosis derived from hepatitis C virus." (PMID 35035671, 2022). "In this study, the effects of human exosomes derived from WJ-MSCs on NOX1, NOX2, and NOX4 gene expression in TGF-β-induced hepatic fibrosis were investigated." (PMID 36544529, 2022). "A recent study indicates that alamandine attenuates liver fibrosis by regulating autophagy induced by NOX4-dependent ROS." (PMID 34571961, 2021). "The ROS-generating enzymes, NADPH oxidase 1 (NOX1), NOX2, or NOX4, can induce liver fibrosis by activating HSCs." (PMID 34675811, 2021). "Compared with WT mice with liver fibrosis, mice in the NOX4−/-+CCI4 and CCI4+ AP groups showed lower collagen deposition (P < .050)." (PMID 34530693, 2021).
liver fibrosis (continued). "In summary, this study showed that the NOX4/NLRP3 inflammasome signaling pathway is essential in the development of liver fibrosis and an important target for the regulation of intestinal bacteria." (PMID 34530693, 2021). "Through this pathway, TGF β 1, PDGF, Met3, and NOX4 play an important role in the process of liver fibrosis." (PMID 34597331, 2021). "Our study showed that NOX4 expression in mice with liver fibrosis was increased, while the degree of fibrosis in NOX4−/- mice was reduced." (PMID 34530693, 2021). "Ang II stimulates NADPH oxidase 4 (NOX4)-derived ROS and mitochondria-dependent ROS accumulation to aggravate hepatic fibrosis by activating HSCs through the IL-1β/NLRP3/Smad pathway and the TLR4/MyD88/NF-κB pathway." (PMID 34944017, 2021). "Based on animal models of liver fibrosis, we explored the effect of intestinal bacteria during liver fibrosis and the effect of NOX4/NLRP3 inflammasome signal." (PMID 34530693, 2021). "To explore the role of the NOX4/NLRP3 inflammasome pathway in liver fibrosis, we measured the expression of NOX4/NLRP3 in the three groups of mice." (PMID 34530693, 2021). "The expression of related fibrotic factors also indicates that NOX4 plays an important role in the development of liver fibrosis." (PMID 34530693, 2021). "UA alleviated liver fibrosis, which manifested as decreases in collagen deposition, liver injury, and the expression of fibrosis-related factors, and the expression of NOX4 and NLRP3 was significantly inhibited by UA treatment." (PMID 34530693, 2021). "To further validate the importance of NOX4 in liver fibrosis, we generated NOX4-/- liver fibrotic mice and injected liver fibrotic mice with the NOX4 inhibitor AP." (PMID 32496208, 2020). "Both NOX4 and RhoA are profibrotic factors that play an important role in liver fibrosis, and they have a close interaction in fibrotic diseases." (PMID 32083022, 2020). "Pathological analysis of mouse liver tissue showed that liver fibrosis and inflammatory infiltration in the NOX4-/- group were significantly reduced compared with those in the CCl4 group." (PMID 32496208, 2020). "In liver fibrotic mice in which NOX4 and RhoA were inhibited, the effect of UA in improving liver fibrosis declined to a certain degree, and the expression of liver fibrosis-related factors was also altered." (PMID 32496208, 2020). "In conclusion, the NOX4/ROS and RhoA/ROCK1 signalling pathways are closely linked to the development of liver fibrosis." (PMID 32496208, 2020). "Here, we used NOX4 knockout mice to better understand the role of NOX4 in the development of liver fibrosis in vivo." (PMID 32496208, 2020). "The results showed that in the liver fibrosis mice treated with NOX4 or RhoA, the disordered intestinal microbiota showed different degrees of improvement." (PMID 32083022, 2020). "The changes in factors related to liver fibrosis were similar, suggesting that UA reverses liver fibrosis by inhibiting the NOX4/ROS pathway." (PMID 32496208, 2020). "By mechanism, Brg1 recruits a variety of histone‐modifying enzymes to change the chromatin structure around the NOX4 site, thus activating its transcription and stimulating liver fibrosis." (PMID 32845093, 2020). "Angiotensin II (Ang II), a key player in RAS, induces the generation of NADPH oxidase 4 (NOX4)/mitochondria-derived ROS and aggravates liver fibrosis, while NLRP3 inflammasome activation is tightly connect with NOX4/mitochondria-derived ROS." (PMID 32211410, 2020). "In the NOX4 intervention and RhoA intervention groups, related experimental analyses confirmed the decrease in CCl4-induced liver fibrosis." (PMID 32496208, 2020). "Injection of NOX4 bioinhibitors into CCl4-induced liver fibrosis in mice reversed the progression of liver fibrosis." (PMID 32496208, 2020). "Although we show that Brg1 promotes EndMT and liver fibrosis through regulating NOX4 transcription and ROS production in endothelial cells, other possibilities cannot be excluded." (PMID 31750301, 2019).
liver fibrosis (continued). "Another notable gene in the most frequent DEG list is Nox4, which plays a key role in the development of liver fibrosis." (PMID 31681434, 2019). "In conclusion, our data uncover a novel epigenetic mechanism that links NOX4-dependent ROS production to EndMT and liver fibrosis." (PMID 31750301, 2019). "The present study investigated the interaction between NOX4/ROS and RhoA/ROCK1 in hepatic fibrosis, the direct binding of NOX4 and RhoA, and the specific antifibrosis molecular targets of UA." (PMID 31130857, 2019). "In in vivo models of liver fibrosis, the levels of NOX4 are up-regulated, as well as in patients with chronic hepatitis C virus derived infection, increasing along the fibrosis degree." (PMID 30250825, 2018). "Accumulating evidence has shown that NADPH oxidase (NOX), NOX-4 in particular, has a key role in the production of free radicals, and, thereby, in the pathogenesis of liver fibrosis." (PMID 28288202, 2017). "Hepatocyte-specific deletion of NOX4 reduced oxidative stress, lipid peroxidation and liver fibrosis in mice." (PMID 26869935, 2016). "In BDL- or CCl4-mediated liver fibrosis, NOX4 expression and its activity are upregulated via a TGFβ-Smad3 dependent manner in HSCs." (PMID 26869935, 2016). "Currently both NOX1 and NOX4 and CYP2E1 are implicated in development of inflammation and liver fibrosis, whereas pharmacological inhibitors of these enzymes have been shown in vivo to prevent hepatocyte death and attenuate fibrosis progression." (PMID 27200149, 2016). "A number of NOX isoforms, including NOX1, NOX2, and NOX4 are involved in the initiation of myofibroblasts activation and progression hepatic fibrosis." (PMID 26869935, 2016). "NOX isoforms, including NOX1, NOX2 and NOX4, and NOX-derived ROS, have all been implicated to regulate HSC activation and hepatocyte apoptosis, both of which are essential steps for initiating liver fibrosis." (PMID 26869935, 2016). "Our results support the concept that both NOX1 and NOX4 play important roles in liver fibrosis in HSCs, and that NOX4 has a more robust role in the activation of HSCs." (PMID 26222337, 2015). "In conclusion, our current study demonstrates that NOX1 and NOX4 signaling mediates hepatic fibrosis through activation of HSCs." (PMID 26222337, 2015). "The overall goal of this study was to determine the roles of NOX1 and NOX4 on the proliferative and fibrogenic phenotypes of HSCs and its contribution to liver fibrosis." (PMID 26222337, 2015). "Our results demonstrate that both NOX1 and NOX4 play important roles in liver fibrosis in HSCs, and that NOX4 has a more robust role in the activation of HSCs." (PMID 26222337, 2015). "Our data demonstrated that NOX1 and NOX4 gene deletion inhibits multiple steps in the pathogenesis of liver fibrosis." (PMID 26222337, 2015). "Consistently, pharmacological inhibition of NOX4 after induction of liver fibrosis in mice was shown to reduce ROS levels and significantly attenuate fibrosis." (PMID 24701562, 2014). "In summary, here we show that NOX4 expression is elevated in the livers of experimental in vivo models of liver fibrosis and in patients with chronic HCV-derived infection, increasing along the fibrosis degree." (PMID 23049784, 2012). "A role for the NADPH oxidases NOX1 and NOX2 in liver fibrosis has been proposed, but the implication of NOX4 is poorly understood yet." (PMID 23049784, 2012). "Taken together, GSH could improve the engraftment efficiency of ADSCs in liver fibrosis by targeting TGFβ1/SMAD3/NOX4 signaling pathway, which provides a new theoretical basis for GSH enhancing ADSC engraftment efficiency in liver diseases." (PMID 40060764, 2025). "In addition, TGF-β-induced ROS production involved in NOX2 and NOX4 signaling activation also contributes to HCV-mediated liver fibrosis and HCC progression." (PMID 37827291, 2023). "NOX4 activates liver fibrosis via regulating ROS to trigger apoptosis and HSC activation." (PMID 36160411, 2022).
liver fibrosis (continued). "NOX4 and reactive oxygen species expressed in HSCs play an important role in liver fibrosis." (PMID 35035671, 2022). "In this study, we found that UA could alleviate CCI4 induced liver fibrosis, and proposed that the beneficial effect of UA on liver fibrosis may be achieved through the NOX4/NLRP3 inflammasome signaling pathway and improving intestinal bacteria." (PMID 34530693, 2021). "We explored the underlying mechanisms involved in this effect and found that the UA-induced reversal of liver fibrosis may be achieved by inhibiting the NOX4/ROS and RhoA/ROCK signalling pathways, which may interact with each other." (PMID 32496208, 2020). "Moreover, because NOX4 can not only generate ROS but also activate HSCs to promote liver fibrosis we added an NOX4 overexpression study in the LX‐2 cells." (PMID 32274310, 2020). "UA can reverse liver fibrosis by inhibiting the NOX4/ROS and RhoA/ROCK1 signalling pathways, which may interact with each other." (PMID 32496208, 2020). "Furthermore, NOX4 can mediate TGF-β and other signalling pathways and induce the activation of resting HSCs and apoptosis in hepatocytes; NOX4 therefore plays an important role in the progression of liver fibrosis." (PMID 32496208, 2020). "In conclusion, our study found that there is a disorder in the intestinal microbiota during liver fibrosis, and this disorder may be related to profibrotic factors NOX4 and RhoA." (PMID 32083022, 2020). "We attempted to identify changes in the intestinal microbiota based on high-throughput sequencing techniques using a mouse model of liver fibrosis and to determine whether these changes have a correlation with the profibrotic factors NOX4 and RhoA." (PMID 32083022, 2020). "This function indicates that NOX4/ROS play an important role in the development of liver fibrosis." (PMID 32496208, 2020). "Actually, NOX1 and NOX4 signaling mediates hepatic fibrosis through activation of HSC." (PMID 30250825, 2018). "Among the NOX family, both NOX1 and NOX4 are expressed in HSCs and may contribute to liver fibrosis." (PMID 26222337, 2015). "Thus, NOX1 and NOX4 signaling mediates the pathogenesis of liver fibrosis, including the direct activation of HSC." (PMID 26222337, 2015). "The effect of NOX1 and NOX4 deficiency in liver fibrosis is unclear, and has never been directly compared." (PMID 26222337, 2015). "In the liver, NOX4 is primarily expressed in hepatocytes, stellate cells and endothelial cells, and plays a pivotal role in the cellular senescence of hepatocytes, hepatitis C virus-induced ROS generation and liver fibrosis." (PMID 24317376, 2014). "The aim of this work was to analyze whether NOX4 expression is modulated in experimental animal models of liver fibrosis and during the development of human liver fibrogenesis." (PMID 23049784, 2012). "However, less is known about the possible role in liver fibrosis of another isoform, NOX4, which is highly expressed in hepatocytes and HSCs." (PMID 23049784, 2012). "Therefore, SME may have a protective effect on liver cells by lowering the expression of NOX4 in nPQ cells, which may prevent liver fibrosis and cell death of PQ cells." (PMID 38001866, 2023). "However, the role of the NOX4/NLRP3 signaling pathway in liver fibrosis has rarely been studied." (PMID 34530693, 2021). "Next, we assessed whether UA could reverse liver fibrosis by suppressing NOX4-related signals." (PMID 34530693, 2021). "Therefore, we generated NLRP3−/- and NOX4−/- mice with liver fibrosis." (PMID 34530693, 2021). "However, it is unknown whether UA directly affects the intestinal microbiota by inhibiting NOX4 and RhoA or indirectly improves the intestinal microbiota by reducing liver fibrosis." (PMID 32496208, 2020). "Therefore, we speculate whether the disorder of intestinal microbiota in liver fibrosis is related to NOX4 and RhoA." (PMID 32083022, 2020). "This suggests that NOX4/ROS may be the upstream signalling pathway of RhoA/ROCK1 in liver fibrosis." (PMID 32496208, 2020).